A4GALT (alpha 1,4-galactosyltransferase (P1PK blood group))
Description:
Glycosyltransferase involved in biosynthesis of P1, P(k) and the rare NOR antigens of P1PK histo-blood group system. Catalyzes the transfer of galactose from UDP-alpha-D-galactose in an alpha1,4 linkage to lactosylceramide/beta-D-galactosyl-(1->4)-beta-D-glucosyl-(1<->1)- ceramide(d18:1(4E)) to produce globotriaosylceramide/globoside Gb3Cer (d18:1(4E)), also known as P(k) antigen or CD77. Globoside Gb3Cer/P(k)/CD77 is a root structure in biosynthesis pathway of neutral glycosphingolipids of the globo-series. Broadly expressed in cell membranes of immune cells and other tissues, Gb3Cer/P(k)/CD77 antigen may participate in mechanisms that regulate cell-cell interactions and cell differentiation. In germinal center B cells, Gb3Cer/CD77 interacts with CD19 to drive centroblast-to-centrocyte transition, B cell receptor complex assembly and T follicular helper cell differentiation. In epithelium, Gb3Cer regulates CDH1/E-cadherin-dependent cell-cell adhesion counteracting epithelial-to-mesenchymal transition (By similarity). Synthesizes P1 glycan epitope (alpha-D-Gal-(1->4)-beta-D-Gal-(1->4)-GlcNAc-R) by transferring a galactose moiety to paragloboside nLc4 or to complex-type N-glycans. Generates the rare NOR1 and NOR2 antigens which carry a Gal(alpha1->4)GalNAc terminal moiety and are both derived from Gb4Cer precursor. Also able to transfer galactose to galactosylceramide/beta-D-Gal-(1<->1')-Cer. (Microbial infection) P1 and Pk antigens are targeted by Shiga toxins (also called verotoxins), as a way to enter the cell, inhibit protein synthesis and induce apoptosis.
Synonyms: A14GALT; A4GALT1; Gb3S; P(k); P1; P1PK; PK
Tractability: Antibody: UniProt predicts a signal peptide or a membrane-spanning region.
Gene: Protein-coding gene on chromosome 22 (42,691,010 to 42,721,298, reverse strand). Ensembl gene ENSG00000128274.
Subcellular location: Golgi apparatus membrane
Subcellular location (Human Protein Atlas): Mitochondria
Pathways (Reactome):
Metabolism: Glycosphingolipid biosynthesis
Gene Ontology:
Molecular function: galactosyltransferase activity; lactosylceramide 4-alpha-galactosyltransferase activity; hexosyltransferase activity; toxic substance binding
Biological process: plasma membrane organization; glycosphingolipid biosynthetic process
Cellular component: membrane; Golgi membrane
Genetic constraint (gnomAD): Loss-of-function variants: 4 observed, 6.49 expected, observed/expected ratio (o/e) 0.62, 90% interval 0.3 to 1.39. That is too few expected variants to judge how well the gene tolerates losing a copy. Missense variants: 512 observed, 495.04 expected, observed/expected ratio (o/e) 1.03, 90% interval 0.96 to 1.11. Synonymous variants: 257 observed, 225.55 expected, observed/expected ratio (o/e) 1.14, 90% interval 1.03 to 1.26.
Homologues: Orthologues: chimpanzee A4GALT (99% identical), macaque A4GALT (96% identical), dog A4GALT (86% identical), pig A4GALT (84% identical), rabbit A4GALT (82% identical), rat A4galt (80% identical), mouse A4galt (77% identical), guinea pig A4GALT (74% identical), Drosophila melanogaster alpha4GT1 (28% identical), Drosophila melanogaster alpha4GT2 (27% identical), Caenorhabditis elegans C01G5.7 (7% identical). Paralogues in human: A4GNT (33% identical).
Diseases named in the same sentence as A4GALT in open-access papers:
A4GALT is named in the same sentence as 25 diseases in open-access papers, as found by Europe PMC text mining. Sharing a sentence is not in itself a finding about the gene and the disease. The quoted sentences say what the papers report.
Fabry disease (7 papers, 2014 to 2026). Fabry disease (FD) is a progressive, inherited, multisystemic lysosomal storage disease characterized by specific neurological, cutaneous, renal, cardiovascular, cochleo-vestibular and cerebrovascular manifestations. "Interestingly, in a symptomatic mouse model of Fabry disease (generated by GLA gene knockout and human A4GALT overexpression), the highest accumulation of Gb3 was found in the spleen and liver, which do not display any abnormalities in the mouse model or patients." (PMID 39511480, 2024).
ovarian carcinoma (3 papers, 2017 to 2024). A malignant neoplasm originating from the surface ovarian epithelium. "It was found that the transcript level of the A4GALT gene (encoding Gb3/CD77 synthase) correlates negatively with mesenchymal characteristics in ovarian cancer." (PMID 39511480, 2024). "In addition, A4GALT, a key enzyme for globoside biosynthesis, can induce EMT and mediate cell–cell adhesion in ovarian cancer cells." (PMID 35151689, 2022).
breast carcinoma (2 papers, 2021 to 2024). "Both our MR and co-localization analyses robustly affirm the association between A4GALT and breast cancer." (PMID 38887235, 2024). "Of the remaining 12 genes, seven (A4GALT, C2ORF74, HRCT1, ZC4H2, ZNF512, ZNF655, and ZNF608) show similar relative expression profiles in large patient samples and other breast cancer cell lines thereby giving insight into predicted role of H3K4me3 mediated gene regulation via the miRNA-mRNA axis." (PMID 34261302, 2021).
colon cancer (2 papers, 2021 to 2026). "A4GALT deficiency was induced by CRISPR-Cas9 mutagenesis in human HCT116 colon cancer cells, and its putative effects tested for proliferation, cell migration and invasion." (PMID 41593565, 2026). "Pharmacological manipulation in vitro using the hypomethylating agent 5-Aza-2-deoxycytidine and histone deacetylase (HDAC) inhibitors induced A4GALT expression in DLD1 colon cancer cells and Gb3 biosynthesis." (PMID 41593565, 2026). "For instance, knockdown of Gb3S (encoded by A4GALT), using siRNA in colon cancer epithelial cells or Shiga toxin in patient-derived gastric adenocarcinomas, decreased the cells’ capacity to migrate and proliferate in vitro and in vivo compared to cells with impaired Gb3 expression." (PMID 33418847, 2021).
colorectal cancer (2 papers, 2024 to 2026). A primary or metastatic malignant neoplasm that affects the colon or rectum. "Gene enrichment analyses revealed that high A4GALT and low α-GLA expression is associated with a distinct gene expression program in gastric, pancreatic and colorectal cancer, including increased signatures of epithelial–mesenchymal transition." (PMID 41593565, 2026).
lung carcinoma (1 paper, 2020). "In contrast to A4GALT, CIB2, and PSMA1, high expression of IRF4 is associated with higher lung cancer patient survival." (PMID 33227088, 2020). "A4GALT, PSMA1, and CIB2 are all among the potential oncogenes identified, since high expression of their mRNAs is significantly associated with lower lung cancer patient survival." (PMID 33227088, 2020). "We are currently exploring this hypothesis and determining the role of A4GALT in lung cancer and its relationship to the RASSF1C-PIWIL1-piRNA pathway." (PMID 33227088, 2020). "Thus, RASSF1C could promote lung cancer cell chemo-resistance through modulation of A4GALT expression." (PMID 33227088, 2020). "In addition, they also suggest that A4GALT and GMIP may be new biomarkers for lung cancer that will be the focus of future investigations." (PMID 33227088, 2020).
meningioma (1 paper, 2023). A generally slow growing tumor attached to the dura mater. "Investigation of antigen distribution across all WHO grades yielded six common meningioma-associated antigens (A4GALT, FBN2, SNED1, MPP6, PCED1B, and ANGEL2)." (PMID 37368072, 2023).
osteoporosis (1 paper, 2022). A condition of reduced bone mass, with decreased cortical thickness and a decrease in the number and size of the trabeculae of cancellous bone (but normal chemical composition), resulting in increased fracture incidence. "However, the association between A4GALT and osteoporosis remains unknown and the biological mechanisms involved are yet to be elucidated." (PMID 35748775, 2022). "In summary, our data demonstrated that rs130347 plays an important role in postmenopausal women with susceptibility to osteoporosis, modulating the epigenetic regulation of a critical osteoporosis-related gene, A4GALT." (PMID 35748775, 2022).
Parkinson disease (1 paper, 2022). A progressive degenerative disorder of the central nervous system characterized by loss of dopamine producing neurons in the substantia nigra and the presence of Lewy bodies in the substantia nigra and locus coeruleus. "A4GALT is involved in regulating the synthesis of glycosphingolipids, which is associated with several neurodegenerative diseases, including AD and Parkinson's disease." (PMID 36776574, 2022).
prostate carcinoma (1 paper, 2024). A carcinoma that arises from epithelial cells of the prostate gland. "Genetic variants of A4GALT are associated with platelet distribution, prostate cancer, red blood cell count, monocyte count, and hemoglobin concentration." (PMID 38172904, 2024).
cancer (6 papers, 2012 to 2026). A tumor composed of atypical neoplastic, often pleomorphic cells that invade other tissues. "RESULTS: A4GALT deficiency in HCT116 cells confirmed its essential role for Gb3 biosynthesis, leading to resistance against Shiga toxin 1a, and to reduced cancer cell migration and invasion." (PMID 41593565, 2026). "A4GALT mediation of glycosphingolipids is essential for the transition of cancer cells from mesenchymal to epithelial to initiate local tumor growth at the metastatic site." (PMID 33227088, 2020). "This raises the interesting hypothesis that the RASSF1C-PIWIL-piRNA pathway may promote reverse transition of metastatic cancer cells from mesenchymal to epithelial to permit local tumor growth at the new site of metastasis via demethylation and up-regulation of A4GALT gene expression." (PMID 33227088, 2020). "Eight proteins (A4GALT, ASIP, CTSF, MARE1, PDXK, SEM4A, PLAUR, VARS1) were observed to have evidence of multi-trait colocalization between the index protein, intermediate phenotypes, and the index cancer endpoint, which may serve to elucidate aetiological pathways to cancer risk." (PMID 38684708, 2024).
tumor (4 papers, 2012 to 2026). "CONCLUSIONS: Our study uncovers an epigenetically regulated lipid metabolic axis involving A4GALT and Gb3 that contributes to aggressive tumor behavior." (PMID 41593565, 2026).
kidney disease (1 paper, 2025). "There were 7 proteins that exclusively associated only with the kidney domain supporting their proximal role in kidney disease (e.g., A4GALT, PCK2, EFNA3, BTN3A2, IDI2, GATM, FAIM)." (PMID 41282674, 2025).
A4GALT also shares sentences with these, for which no sentence is quoted: bacterial infection (2 papers); infection (2); Encephalopathy (1); gastric adenocarcinoma (1); Hypervolemia (1); lymph node metastases (1); lymphoma (1); neurodegenerative disease (1); osteoarthritis (1); pancreatic adenocarcinoma (1); primary aldosteronism (1); systemic lupus erythematosus (1).